LIMK1 (LIM domain kinase 1)
Diseases named in the same sentence as LIMK1 in open-access papers (continued):
Sharing a sentence is not in itself a finding about the gene and the disease.
infection (7 papers, 2013 to 2025). The state of being infected such as from the introduction of a foreign agent such as serum, vaccine, antigenic substance or organism. "For other viruses, LIMK1 was recently implicated in infection by influenza A virus, pseudorabies virus, and herpes simplex virus 1 (HSV-1)." (PMID 28381571, 2017). "However, the phosphorylation levels of vimentin, vinculin, paxillin, and LIM domain kinase 1 were upregulated at 6 h and 36 h after infection." (PMID 38759153, 2024). "In the case of JEV infection, it has been shown that entry is independent of clathrin, while the regulatory proteins of actin filaments, such as RHOA, RAC1, proteins of the ARP2/3 complex, and the N-WASP family (LIMK1, PAK1, and ROCK2), are crucial for the establishment of infection." (PMID 40733526, 2025).
cardiac diseases (2 papers, 2019 to 2024). "Nevertheless, the expression of LIMK1 in CFH or other cardiac diseases are scarcely explored." (PMID 31541994, 2019).
genetic disorder (2 papers, 2018 to 2024). "The cardiovascular pathology present in Williams–Beuren syndrome (a genetic disorder caused by heterozygous deletion of genes including LIMK1 at chromosome 7q11.23) appears to depend on the heterozygous deletion of the elastin gene and not that of LIMK1." (PMID 39744707, 2024).
neurological diseases (2 papers, 2014 to 2019). "Indeed, chemical modulators for Cdc42, LIMK1, and GSK3β are currently available and several FDA-approved GSK3β inhibitors are already being used in the treatment of neurological diseases." (PMID 31134199, 2019).
adenocarcinoma (1 paper, 2011). A common cancer characterized by the presence of malignant glandular cells. "We noted increased expression of LIMK1 and MT1-MMP in the tissues from the same tumors showing adenocarcinoma with Gleason scores 9/10 compared to the normal epithelium." (PMID 21219645, 2011).
brain disorder (1 paper, 2021). A disease affecting the brain or part of the brain. "Given the role of LIMK1 in the regulation of actin dynamics, dendritic spines, synaptic plasticity, and learning and memory, it is not surprising that deficits in LIMK1 are implicated in a wide range of brain disorders." (PMID 34440848, 2021). "In addition, changes in LIMK signaling, including upstream regulators and downstream targets, are widely reported in brain disorders and in some cases, manipulations of LIMK1 improve synaptic and behavioural functions associated with these disorders." (PMID 34440848, 2021).
LIMK1 also shares sentences with these, for which no sentence is quoted: neurodegenerative disease (4 papers); Parkinson disease (4); depression (3); cardiovascular disease (2); erectile dysfunction (2); leukemia (2); metastatic cancer (2); neurodevelopmental disorder (2); oral cancer (2); primary pulmonary hypertension (2); acute lymphoblastic leukemia (1); acute myeloid leukemia (1); AIDS (1); allergic disease (1); anaphylaxis (1); Andersen syndrome (1); aneurysm (1); Ascites (1); brain tumour (1); cervical adenocarcinoma (1); choriocarcinoma (1); chronic heart failure (1); cognitive disorder (1); diabetic encephalopathy (1); dopaminergic neuroblastoma (1); endometrial cancer (1); Ewing sarcoma (1); fibrosarcoma (1); glaucoma (1); Hantavirus infection (1).
A further 42 diseases each share a sentence with LIMK1 in 1 paper.